CD4 (CD4 molecule)
Diseases named in the same sentence as CD4 in open-access papers (continued):
Sharing a sentence is not in itself a finding about the gene and the disease.
tumor (continued). "Relationship between survival of GCs patients and tumor infiltration Tregs was observed negative in general whatever on the basis of the ratio of Tregs/CD4+ lymphocyte or Tregs/lymphocytes in this article." (PMID 32231740, 2020). "Besides the high specificity to DCs, such vaccines have been shown to effectively induce anti-tumor CD8+ and CD4+ T cell and humoral immune responses in mice in a lower dose, compared with the administration of non-targeted antigens." (PMID 32150821, 2020). "Although the percentages of CD4+ or CD8+ T cells in the bronchial dLNs were comparable between KP and KP7 mice at 10 weeks after tumor induction, the numbers of CD4+ or CD8+ T cells were significantly decreased in bronchial dLNs from KP7 mice compared to KP mice." (PMID 33257678, 2020). "On the other hand, it was shown that CD4+ T cells expressing an MHC class I‐restricted TCR provide important additional TCR functions, such as increased IL‐2 help, and thereby contribute to an increased anti‐tumor response." (PMID 33251011, 2020). "In addition, using the TIMER algorithm, we found that expression of TMEM150B, SIGLEC1, and CTSW correlated positively with the tumor infiltration levels of B cells, CD8+ T cells, CD4+ T cells, macrophages, and dendritic cells." (PMID 32074080, 2020). "Despite increases in the total CD45+ tumor infiltrating immune cells, the percentage of CD4+ and CD8+ T cells were not changed by IL36 or combined administration of IL36 and CTLA-4 mAbs." (PMID 32351508, 2020). "Tumor protection requires cell surface CRT, as well as CD8+ and CD4+ T cells." (PMID 33330069, 2020). "In tumor tissues, Tregs were highly correlated with T cells CD8, B cells memory and T cells follicular helper, and negatively correlated with plasma cells, T cells CD4 memory resting and dendritic cells." (PMID 32850758, 2020). "As a negative regulatory molecule, It has been confirmed that Tim3 can be expressed on a variety of immune cells, such as CD4+T cells (Th1, Th17), CD8+T cells, Treg cells, DCs, monocytes, mast cells, macrophages, NK cells, and plays an important role in tumor immunity in tumor microenvironment." (PMID 33330064, 2020). "Analysis of surgical tissues and peripheral blood before and after treatment showed that anti-CTLA-4 treatment could induce ICOS pathway activation, and CD4+ICOS+T cells could produce IFN-γ and recognize tumor antigens." (PMID 32864131, 2020). "In addition, a significant positive correlation between the ratio of CD4+/CD8+ T cells and tumour weight was observed upon histamine treatment in H4R-KO mice, further demonstrating the crucial role of H4R in immunosurveillance." (PMID 31748740, 2020). "This may explain the increased proportion of CD4+/Foxp3+ Treg in PLNs, accompanied by a decreased proportion of CD8+ T lymphocytes in PLNs and the tumor infiltrate, from T. canis infected mice." (PMID 32547942, 2020). "Although CD4+ T cells increased approximately 30% in both IL-15 and IL-15cx treated mice compared to control tumor mice, the difference was not statistically significant." (PMID 33628206, 2020). "The stimulation of apoptosis during mEHT treatments could result in antigen presentation promoting the generation of CD4+ and CD8+ T-cells in situ inside the tumor." (PMID 33014841, 2020). "• Serial tumor biopsies before and after PD-1 blockade identifies chromatin regulators of therapy-responsive T cell subsets and reveals a shared regulatory program that governs intratumoral CD8+ T cell exhaustion and CD4+ T follicular helper cell development." (PMID 32265933, 2020). "In our study, ILT4 did not alter CD4+ T cell frequency, possibly due to complex CD4+ T subset components and their conflicting effects on anti-tumor immunity." (PMID 32368343, 2020). "A new CXCL13+BHLHe40+ Th1‐like CD4+ subset was found to be present at higher proportion in MSI tumor and may explain higher IFN‐γ level in MSI tumor and better response of these patients to anti‐PD‐1 treatment." (PMID 32272497, 2020).
tumor (continued). "For instance, IL-33 release in murine HCC showed to markedly inhibit tumor growth via activated CD4+ and CD8+ T cells, in IL-33-expressing tumor-bearing mice, while IL-18/IL-12 cytokine therapy was effective in tumor regression prompted by induction of NK cells." (PMID 32899197, 2020). "In addition, patients responding to ICIs have high pre-treatment levels of CD4+ and CD8+ T cells in the tumor parenchyma in proximity to the tumor cells, a patient profile defined as an immune-inflamed phenotype (“hot” tumor)." (PMID 32998446, 2020). "The CD4+ cell proportion and CD4+/CD8+ cell ratio in tumor tissue were significantly reduced." (PMID 32131750, 2020). "Immunohistochemical staining of tumor tissues showed that DTT-COS12 treatments had a more positive area with anti-CD8 than control, and in contrast less positive area with anti-CD4." (PMID 32423130, 2020). "Moreover, FACS staining indicated that both CD4+ and CD8+ T cells expressed increased levels of the activation marker PD1, which is suggestive of tumor-specific T cells, compared with circulating T cells (CD8+PD1+ T cells; CD4+PD1+ T cells, P < 0.05)." (PMID 32814714, 2020). "The localization of the CD4+Foxp3+ and CD4+LAG3+ T-cells remains instead more controversial, but it may be dictated by the expression of MHC-II on tumor cells." (PMID 33327433, 2020). "CD4-positive T cells and CD8-positive T cells are involved in the tumor immune environment in OS." (PMID 32751195, 2020). "Furthermore, Bregs TGF-beta production can drive conversion of CD4+ T cells to Tregs leading to inhibition of CD8+ T cells and Natural Killer (NK) cells, both of which are important for limiting tumor growth." (PMID 33193299, 2020). "Also, adoptive transfer of IL-21-producing CD4+ T cells into tumor-bearing mice induced generation of a CX3CR1+ effector CD8+ T cell pool, leading to improved tumor control." (PMID 33123174, 2020). "The oncolytic group B adenovirus EnAdenotucirev (EnAdV) was modified by Freedman and colleagues to express another BiTE coordinately binding EpCAM+ tumor cells and CD3+ T cells, leading to clustering and activation of both CD4+ and CD8+ T cells with tumor cells." (PMID 32664210, 2020). "Afterwhile, we assessed whether YYWY could induce DC's CD4 and CD8+ T cell expression in tumor-bearing mice." (PMID 32595493, 2020). "A recent paper reported that the activity of tumor antigen-specific CD8+ and CD4+ T cells could induce antitumor response in immunotherapy." (PMID 32754579, 2020). "Further analysis of CD8+ and CD4+ T-cell populations revealed that mice treated with both anti-CAIX CAR-T cells and LB-100 demonstrated significantly higher quantities of CD8+ and CD4+ T cells at the tumor site." (PMID 31935881, 2020). "Moreover, analysis of human tumor-infiltrating CD4+ T cell transcriptomes, confirmed CYP11A1 expression implying that CD4+ T cells are a source of steroids in tumors, mirroring the murine setting." (PMID 32680985, 2020). "As in previous results, we observed an increase in the proportion of intratumor CD8+ T cells; whereas, no significant changes were seen in the frequency of tumor-infiltrating CD4+ T cells." (PMID 33126649, 2020). "Moreover, RT can lead to increased tumor antigen release, improved antigen presentation, upregulated PD1 expression and increased CD8/CD4 ratio in TME." (PMID 32650830, 2020). "Specific depletion of this subset of TAMs by the anti-CD163 lipid nanoparticles containing doxorubicin resulted in reduced tumor growth and increased infiltration of monocytes and immature TAMs that advance inflammatory responses and recruitment of CD4+ and CD8+ T cells promoting tumor regression." (PMID 32752088, 2020). "Tumor-infiltrating lymphocytes expressing CD8, CD4 and Forkhead box 3 (Foxp3) were detected by IHC." (PMID 32284765, 2020). "We discovered that YAP plays a role in non-Treg T cells through tumor studies of the YAP fl/fl CD4 Cre and YAP FoxP3 YFP Cre animals (T cell and Treg-specific deletion of YAP)." (PMID 32322254, 2020).
tumor (continued). "The characteristics and the role of CD4+ TRM (non-Treg) cells in anti-tumor immunity is not well understood." (PMID 33379384, 2020). "Furthermore, these altered M2-like macrophages were able to cause a significant increase in the levels of IFNγ produced from co-cultured CD4+ T cells, and also significantly increased granzyme B release from CD8+ T cells in response to tumor cells." (PMID 32455916, 2020). "However, AdIL-17A-transduction also induced strong organ-specific and time-dependent immune activation indicated by dynamic changes of NK cells, B cells, CD4, and CD8 T cells in peripheral blood, lung, and tumor site, as well as the plasma levels of IFNγ." (PMID 32770025, 2020). "There was no positive correlation between macrophage M0 and other cells in tumor tissues, only T cells CD4 memory resting and T cells CD8 had negative correlation with it." (PMID 32850758, 2020). "Furthermore, we detected higher levels of IFN-γ and TNF-α expression in tumor-infiltrating CD4+ and CD8+ T cells in Fip200–/– tumor-bearing mice compared with WT tumor-bearing mice." (PMID 32780724, 2020). "However, tumors with high levels of C5a present an accelerated tumor growth with less CD4+ and CD8+ T cells, in the tumor, the spleen and the tumor-draingin lymph nodes." (PMID 33113844, 2020). "Strikingly, depletion of CD8+ T cells was not sufficient to abrogate response to ICB, while no tumor showed ICB-induced regression after depletion of CD4+ T cells." (PMID 32071302, 2020). "The role of CD4+ T cells having cytotoxic effects independent of other T cells on tumor is now becoming increasingly clear in many cancers including liver cancer." (PMID 32636725, 2020). "In terms of characteristics of killing dynamics, CD4 CAR T cells show initial slower granzyme B secretion and tumor killing, but are less prone to AICD and exhaustion compared to CD8 counterparts, which confers CD4 CAR T cells a relative better persistence following antigen exposure." (PMID 33292660, 2020). "Combination therapy using anti-PD-1 antibody and an inhibitor of CXCR4, a receptor for CXCL12/SDF-1 that contributes to the maintenance of tumor stem cells, also increases local infiltration of CD4/8 T cells by suppressing Treg and MDSC tumor invasion and prolongs the survival of tumor-bearing mice." (PMID 32707672, 2020). "Augmented infiltration of CD3+, CD4+ and CD8+ T cells was also observed, compared with anti-programmed cell death protein 1 (PD-1) monotherapy, while TRIMELVax/anti-PD-1 combination generated higher tumor infiltration of CD4+ T cells." (PMID 32690772, 2020). "The number of Tregs in the tumor, to a large extent, depended on the abundance of CD4+ TILs but not CD8+ TILs." (PMID 33457428, 2020). "Further, we confirmed that Mn-insufficient mice were much more vulnerable to B16F10 tumor invasion compared to the control mice, as indicated by the greatly increased tumor size and weight with significantly reduced tumor-infiltrating CD8+ and CD4+ T cells (TILs) in tumors." (PMID 32839553, 2020). "Although the anti-tumor immunity is primarily executed by CD4 T cells, CD8 T cells, and natural killer (NK) T cells, B cells are also seen within the TME of some tumors, and patients often develop IgG that is specifically reactive with tumor antigens." (PMID 33167384, 2020). "Ipilimumab binds to CTLA-4 on T-cells, which inhibits its ability to bind to CD80/CD86, allowing for the expansion of a repertoire of antigen-specific anti-tumor cytotoxic CD8+ T-cells and CD4+ T-cells, which corresponds to an improved anti-tumor immune response." (PMID 33256089, 2020). "Mice with EGFR-19 del LLC cell tumours had lower numbers of CD8+ and CD4+ cells." (PMID 33143170, 2020). "The observations suggest that while CD4+ T cell depletion had a minor impact, CD8+ T cell depletion resulted in markedly enhanced tumor growth, showing, as expected, that CD8+ T cells provide endogenous tumor control." (PMID 33298945, 2020).
tumor (continued). "In addition to the role of tumor neoantigen-specific CD8+ T cells in cancer elimination through MHC class I, enhanced antitumor activity requires activation of CD4+ T cells via MHC class II in response to immunotherapy." (PMID 33255891, 2020). "Even though our data support a functional role for CD4+ T cells in effective anti-parasite immunity, the fibrinogen-like protein 1 (FGL-1) appears as a major ligand of LAG-3 that works independently of MHC-II, and inhibits T cell-mediated anti-tumor immunity." (PMID 33519801, 2020). "While a small increase in CD4+ FOXP3+ CD25+ Tregs was observed in the MC38 TNRs when compared to the control treated tumours this was not significant." (PMID 32705455, 2020). "This may be because other hematopoietic cells, such as NK and CD4+ T cells, also produce IFN-γ within the tumor." (PMID 32547942, 2020). "There was no significant change in CD8+Ki67+, CD8+Granzyme B+, CD4+, and Foxp3+ (Treg) T cells compartment in the spleen and tumor." (PMID 32780726, 2020). "T cells present in tumour are mixtures of CD8+ T cells and CD4+ T cells." (PMID 33170901, 2020). "GL261 tumors showed the lowest frequency of KLRG1+ cells and CD25+ cells of the CD4 subset, whereas 70–80% of CD8 T cells in CT2A were positive for Lag3 and Tim3, markers of dysfunctional T cells in comparison to the other tumor types analyzed." (PMID 32764562, 2020). "Furthermore, ATCT of TH9 cells in advanced B16-OVA melanoma tumor-bearing mice revealed that these cells exert potent effector functions, which are distinct from TH1 and TH17 CD4+ T cell subsets, and express less exhaustion markers (i.e. PD-1 and LAG3)." (PMID 33584721, 2020). "Expansion of an ICOS+ TH1-like CD4+ effector subset was observed in response to CTLA4 blockade; therefore, TH cells, particularly the TH1 cells, are also pivotal players in T-cell mediated anti-tumor immunity and can respond to immunotherapy." (PMID 33329692, 2020). "[Fabaceae] (GP) could reduce the frequency of CD4+CD25+ Tregs and Foxp3 expression, but increase the ratio of Th1/2 cytokines in serum, which partially contributes to GP-mediated inhibition of tumor growth." (PMID 32733246, 2020). "Although CD4+ T-cells plays important roles in anti-tumor immunity, there is solid pre-clinical evidence that triggering CD8+ CTLs is important for the elimination of tumor cells." (PMID 32075165, 2020). "Furthermore, regarding tumor microenvironment (TME) immunomodulation, DTT-COS1 treatment increased the proportion of CD4+ effector T cells (Teff) and decreased the expression of a suppressive cytokine." (PMID 32423130, 2020). "We further examined the proportions of CD4+ T cells, CD8+ T cells, Foxp3+ regulatory T lymphocytes (T-regs), and IFN-γ+ cytotoxic T lymphocytes (CTLs) in the different groups of tumor tissues to determine the effects of miR-200a on anti-tumor immunity in vivo." (PMID 31981455, 2020). "In EPIC, the proportion of CAFs showed a tendency to increase with tumor stage and grade progression, but the proportion of CD4+ and CD8+ T cells had no significant change in KIRC." (PMID 33634098, 2020). "Moxibustion upregulated the infiltration of CD4+ T cells and Th1 cells in the tumor, and the combinatorial therapy increased the proportion of CD8+ cytotoxic T cells (CTLs), CD4+T cells, Th1, Th9 cells, and M1 macrophages, as well as the expression of Cd69, Ifng, and Cd86 mRNA." (PMID 33456484, 2020). "For an anti‐cancer immune response to generate efficiently, dendritic cells (DCs) are required to migrate from the tumor site to secondary lymphoid organs (SLOs) and present major histocompatibility complex (MHC) molecule–peptide antigen complexes to CD4+ and CD8+ T cells." (PMID 33251010, 2020). "Notably, this effect implicates an early tumor-infiltration of CD8+ T cells and a continuous impact of CD4+ T cells throughout the disease course." (PMID 32117316, 2020).
tumor (continued). "Interestingly, complete tumor rejection was observed in a subset of MIF−/− mice that coincided with significant decreases in Tregs and corresponding increases in splenic CD4+ and CD8+ lymphocytes." (PMID 33324425, 2020). "We found that PD-1, LAG-3 and Tim-3 were the three most upregulated checkpoint receptors on non-Treg CD4+ and CD8+ TILs as compared to autologous peripheral T cells, whereas PD-1, CTLA-4 and LAG-3 were dominant on tumor-associated Tregs." (PMID 32582215, 2020). "Hence, specific T lymphocyte markers such as CD3,CD4,CD8 were carried out on RB tumors (n = 12) and different regions (Tumor lobule, tumor blood vessels, Retinal blood vessel, invading front, Necrotic area) were analysed." (PMID 32576886, 2020). "Thus, both CD4+ and CD8 T cells showed evidence of increased activation and proliferation in tumours of Fgf2LMW−/− mice." (PMID 32792542, 2020). "In addition, we found only a weak correlation linking the proportion of tumor-reactive CD8+ and CD4+ TILs in each sample (r = 0.23, p < 0.0017, n = 177)." (PMID 33198174, 2020). "In addition, combination treatment with a CCL2 antagonist and anti-PD1 antibody enhanced CD4+ and CD8+ T cell infiltration, as well as the production of IFNγ, and increased the survival time of tumor-bearing mice." (PMID 32005273, 2020). "However, the ratio between CD4: and CD8 in expanded TILs depends on the type of tumor as well as the culturing methods and can result in a heterogeneous ratio within the same study." (PMID 32814714, 2020). "CD3+ T cells (which include both CD4+ T cells and CD8+ T cells), CD8+ T cells, immunosuppressive CD3+FOXP3+ regulatory T cells (Tregs), and CD20+ B cells in the tumor nest and surrounding stroma were profiled and quantified by an automated quantitative pathology imaging system." (PMID 33352665, 2020). "• In DTC, the extent of tumor-infiltrating CD4+ cells does not seem to predict the patient’s prognosis." (PMID 33193087, 2020). "Low affinity TCRs targeting TAAs have produced limited anti-tumor function and proliferation in CD8+ T cells, and lack capability to redirect CD4+ T cells to MHC class I-restricted epitopes, which requires higher TCR affinities than most naturally occurring TCRs." (PMID 32570906, 2020). "αβ T cells, including CD4+ T cells and CD8+ T cells, have been extensively studied in tumor immunity, but the role of γδ T cells in the tumor microenvironment (TME) is largely unknown." (PMID 33101298, 2020). "CD4 T cells and CD8 cytotoxic T cells were observed in low numbers in the tumor stroma." (PMID 32994412, 2020). "However, a study has shown that HBV-specific CD4 T cells are less cytotoxic to HCC cells and suppress the anti-tumor function of CD8 T cells." (PMID 33425905, 2020). "Once they reach the tumor microenvironment, neutrophils may undergo transition to MDSCs that inhibit CD4+ and CD8+ tumor-infiltrating lymphocytes, as well as stimulating tumor growth, angiogenesis and metastasis." (PMID 33194755, 2020). "However, as our in vitro data show, both CD4 and CD8 can mediate anti-tumor-reactivity, which is also in line with earlier findings." (PMID 32547707, 2020). "Since we have seen that combination therapy led to the expansion of functional CD8+ T cells in the tumor, we sought to determine if tumor suppression is indeed dependent on CD8+ T cells by depleting each immune cell type including CD4+ T, CD8+ T cells, and NK cells." (PMID 33584714, 2020). "A2BR blockade promotes DC activation (e.g., increased CD86 expression on CD11b- DCs), increases CD4+ and CD8+ T cell IFN-γ production, and tumor cell IFN-γ and CXCL10 expression, which supports the therapeutic potential of A2BR antagonists in enhancing antitumor immunity." (PMID 32351498, 2020). "CD4+ T cells, on the other hand, do not recognize tumor cells directly due to the lack of MHC II on solid tumor cells." (PMID 33584650, 2020).